ARHGAP40 (Rho GTPase activating protein 40)
Description:
GTPase activator for the Rho-type GTPases by converting them to an inactive GDP-bound state.
Synonyms: C20orf95; dJ1100H13.4
Tractability: Antibody: the Human Protein Atlas places it where antibodies can reach. PROTAC: ubiquitination databases record sites on it.
Gene: Protein-coding gene on chromosome 20 (38,601,775 to 38,651,035, forward strand). Ensembl gene ENSG00000124143.
Subcellular location (Human Protein Atlas): Cytosol; Plasma membrane; Centrosome; Nucleoplasm
Pathways (Reactome):
Signal Transduction: CDC42 GTPase cycle; RHOA GTPase cycle
Gene Ontology:
Molecular function: GTPase activator activity
Biological process: regulation of actin filament polymerization; regulation of small GTPase mediated signal transduction; signal transduction
Cellular component: cytoplasm; cytosol
Genetic constraint (gnomAD): Loss-of-function variants: 38 observed, 69.36 expected, observed/expected ratio (o/e) 0.55, 90% interval 0.42 to 0.72. The upper end of that interval is the gene's LOEUF score, 0.72, which puts it in group 2 of 6, group 1 being the genes least tolerant of losing a copy. Missense variants: 661 observed, 796.81 expected, observed/expected ratio (o/e) 0.83, 90% interval 0.78 to 0.88. Synonymous variants: 272 observed, 327.42 expected, observed/expected ratio (o/e) 0.83, 90% interval 0.75 to 0.92.
Homologues: Orthologues: macaque ARHGAP40 (91% identical), chimpanzee ARHGAP40 (91% identical), mouse Arhgap40 (74% identical), rat Arhgap40 (74% identical), tropical clawed frog arhgap40 (45% identical), Drosophila melanogaster conu (20% identical). Paralogues in human: ARHGAP18 (36% identical), ARHGAP28 (33% identical), ARHGAP19 (15% identical).
Diseases named in the same sentence as ARHGAP40 in open-access papers:
ARHGAP40 is named in the same sentence as 7 diseases in open-access papers, as found by Europe PMC text mining. Sharing a sentence is not in itself a finding about the gene and the disease. The quoted sentences say what the papers report.
cancer (3 papers, 2021 to 2022). A tumor composed of atypical neoplastic, often pleomorphic cells that invade other tissues. "There were no researches about the roles of FUT7, PADI1, PPL, and ARHGAP40 in LSCC, but the roles of these genes or the related genes in other cancers were reported." (PMID 34131588, 2021).
ARHGAP40 also shares sentences with these, for which no sentence is quoted: Cirrhosis (1 paper); laryngeal squamous cell carcinoma (1); liver cancer (1); non-small cell lung carcinoma (1); sclerosing cholangitis (1); thyroid cancer (1).